RNU6-289P (RNA, U6 small nuclear 289, pseudogene)
Gene: Small nuclear RNA gene on chromosome 4 (111,331,412 to 111,331,518, forward strand). Ensembl gene ENSG00000200963.
Homologues: Orthologues: chimpanzee U6 (99% identical), macaque U6 (96% identical), guinea pig U6 (77% identical). Paralogues in human: RNU6-116P (83% identical), RNU6-140P (83% identical), RNU6-345P (83% identical), RNU6-1316P (82% identical), RNU6-29P (82% identical), RNU6-310P (82% identical), RNU6-641P (82% identical), RNU6-664P (82% identical), RNU6-698P (82% identical), RNU6-1075P (81% identical), RNU6-1145P (81% identical), RNU6-181P (81% identical), and 1287 more.